CRP (C-reactive protein)
Diseases named in the same sentence as CRP in open-access papers (continued):
Sharing a sentence is not in itself a finding about the gene and the disease.
Hyponatremia (continued). "Inflammation (a raised CRP > 6 mg/l), has been found as an important predictor of hyponatremia and also MIS is inversely correlated with sNa level." (PMID 33511145, 2020). "The common abnormal indicators (abnormal rate ≥ 50%) included: increased neutrophil ratio (50%), increased monocyte ratio (75%), hypokalemia (50%), hyponatremia (50%), hypoproteinemia (75%), and increased C-reactive protein (83.3%)." (PMID 32754610, 2020). "Particularly, male sex, hyponatraemia, increased aspartate aminotransferase (AST), and C-reactive protein (CRP) were confirmed as the risk factors favor IVIG resistance in Mongoloids from Asia countries, but not in Caucasians from non-Asia regions." (PMID 32373568, 2020). "The liver enzyme levels were elevated, and slight hyponatraemia (up to 130 mmol/l) was observed, but the C-reactive protein (CRP) level was normal." (PMID 31690266, 2019). "In univariate analyses, children with hyponatremia were significantly older (P < 0.0001), more likely to be male (P = 0.019), and had higher CRP levels (P < 0.0001) and coinfections with multiple organisms (P = 0.001) than children without hyponatremia." (PMID 30405154, 2018). "Patients with JSF were more likely than patients with ST to have low platelet counts; elevated bilirubin, creatinine kinase, blood urea nitrogen, and creatinine levels; hyponatremia; and high C-reactive protein." (PMID 30124190, 2018). "The AUC values of age (0.586, P < 0.0001), CRP (0.599, P < 0.0001), and blood urea nitrogen (0.559, P < 0.0001) were all significant predictors of hyponatremia." (PMID 30405154, 2018). "Initial blood test results showed mild hyponatremia (132 mEq/L) and an elevated C-reactive protein (CRP) (88 mg/L) and erythrocyte sedimentation rate (ESR) (104 mm/h)." (PMID 28219414, 2017). "Her blood tests at that time showed a normal white blood cell (WBC) count (5.2 × 109/L), mild hyponatremia (sodium level 133mEq/mL), and elevated levels of C-reactive protein (CRP) (16.23mg/dL) and lactate dehydrogenase (LDH) (950U/L)." (PMID 26044457, 2015). "As well as body temperature and CRP level, hyponatremia is a relevant and specific marker of infectious colon perforation in patients older than fifty years." (PMID 23476637, 2013). "In general, patients with moderate-to-severe hyponatraemia presented more ill, as illustrated by their higher body temperatures, pulse rates, CRP and creatinine levels." (PMID 22280539, 2012). "Previously, a relationship between a rise in CRP and the development of in-hospital hyponatraemia was demonstrated." (PMID 22280539, 2012). "There was mild hyponatremia (133 mmol/L) and worsening C-reactive protein levels (179.9 mg/L) but a stable creatine kinase (50 u/L)." (PMID 15030694, 2004). "Major predictors include high serum ammonia levels, high MELD or MELD-Na values, indications of renal impairment with high creatinine, hyponatremia, systemic inflammatory markers, including C-reactive protein (CRP)q or white blood cell count, and Acute-On-Chronic Liver Failure (ACLF) scores." (PMID 40786415, 2025). "In patients with intestinal necrosis, the WBC (p = 0.034), blood glucose (p = 0.040), Scr (p < 0.001), LDH (p < 0.001), CRP (p < 0.001), and D‐dimer (p < 0.001) levels were higher, the incidence of hyponatremia was higher (p = 0.032), and albumin levels were lower (p = 0.006)." (PMID 41498031, 2025). "By the second postoperative week, she exhibited hyponatremia, hypokalemia, metabolic acidosis, gastrointestinal and mucosal bleeding (notably involving the gastric mucosa, lips, tongue, and pharynx), pancytopenia, and elevated C-reactive protein (CRP) levels." (PMID 40492259, 2025). "The Laboratory Risk Indicator for Necrotizing Fasciitis (LRINEC) score, retrospectively calculated as 10, indicated a high probability of necrotizing fasciitis (>75%) based on elevated white blood cell count (26.6 x 103/μL), C-reactive protein (423.40 mg/L), and hyponatremia." (PMID 40821270, 2025).
Hyponatremia (continued). "Among patients who developed hyponatremia, the median C-reactive protein value was notably higher (4.3 mg/dL [95% CI, 1.2-10.3 mg/dL]) compared with those without hyponatremia (1.3 mg/dL [95% CI, 0.3-5.3 mg/dL]) (to convert to milligrams per liter, multiply by 10.0)." (PMID 39680412, 2024). "Laboratory tests showed pancytopenia (leukopenia with lymphopenia, neutropenia, anemia, and thrombocytopenia), marked indications of inflammatory syndrome (CRP 247 mg/L, procalcitonin 10 ng/mL) and metabolic acidosis (pH 7.32, bicarbonate 16.3 mmol/L), and hyponatremia (127.5 mmol/L)." (PMID 38541872, 2024). "Most patients presented with elevated CRP levels and showed a tendency toward hyponatremia." (PMID 37854473, 2023). "Finally, we performed a comparison between subjects with mild hyponatremia and subjects with moderate to severe hyponatremia that showed a higher value of CRP in the latter group (161.0 ± 148.8 mg/L vs. 54.7 ± 64.7 mg/L; p < 0.001 not shown in tables)." (PMID 37353742, 2023). "At present, the widely-accepted diagnostic models for IVIG resistance in KD, including Gunma, Kurume, and Osaka scorings, are primarily based on patient clinical data, such as increased neutrophil counts, decreased platelet counts, hyponatremia, hepatic dysfunction, and elevated CRP levels." (PMID 36989310, 2023). "The strongest predictors were elevated LDH, elevated CRP and hyponatremia." (PMID 35534798, 2022). "The association between hyponatremia and convulsions was not statistically significant (adjusted OR 3.10 [95% CI 0.93–10.36], p = 0.066), as well as the associations of CRP and gestational age at birth with convulsions (p = 0.166 and 0.217, respectively)." (PMID 34354134, 2021). "(ii) Although distinctive and reliable markers for a PA or AA are lacking, our data indicate that a raised C-reactive protein (CRP), hyponatremia, and Tzanakis score may predict a PA." (PMID 34222491, 2021). "A multivariable logistic regression model was conducted including the variables hyponatremia, high blood glucose level (glucose > 120 mg/dL), CRP levels, severity of AGE (Vesikari score ≥ 11), highest body temperature and gestational age at birth as the independent variables." (PMID 34354134, 2021). "Meanwhile, the inflammation associated hyponatremia also occurred in non-malignant diseases, in which hyponatremia was correlated with neutrophil counts, CRP, IL-1β, and IL-6 levels." (PMID 33552948, 2020). "Furthermore, compared to SARS-CoV-2-negative patients, they developed a lower lymphocyte count, platelet count and hyponatremia, and higher CRP and ferritin level (all of them statistically significant)." (PMID 33105634, 2020). "Blood workup revealed leucopenia, hyperbilirubinemia, hyponatremia, and elevated CRP." (PMID 33425398, 2020). "CRP increased the odds ratio of hyponatremia by a small amount (OR 1.093)." (PMID 30405154, 2018). "Moreover, patients with hyponatremia showed signs of more advanced cirrhosis compared to patients without hyponatremia and, in addition, leukocyte count and C-reactive protein (CRP) levels were also higher in patients with hyponatremia." (PMID 25643318, 2014). "Regarding symptomatology, hyponatremia in SARS-CoV-2 positive patients was associated with a greater predisposition to fever and nausea, and in terms of biological changes, with increased leukocytes, neutrophils and high sensitivity C-reactive protein (HS-CRP)." (PMID 33435405, 2021). "In addition, she also had mild hyponatremia and elevated C-reactive protein." (PMID 15030694, 2004). "Laboratory tests revealed an elevated C-reactive protein (CRP) level of 4.89 mg/dL, eosinophilia (13.0%, 670/μL), and hyponatremia (serum sodium 133 mmol/L)." (PMID 41244903, 2025). "Initial laboratory investigations showed an elevated C-reactive protein (CRP) of 237 mg/L, white cell count (WCC) of 14.4x109/L, serum bilirubin of 27 μmol/L, alanine aminotransferase (ALT) of 152 U/L, and hyponatremia with a sodium level of 126 mmol/L." (PMID 40821318, 2025).
Hyponatremia (continued). "Laboratory results were significant for hyponatremia with sodium 126 mEq/L and an elevated erythrocyte sedimentation rate (ESR) of 43 mm/hr and C-reactive protein (CRP) of 12 μg/mL." (PMID 40895018, 2025). "MCD patients, who have higher expression levels of hIL-6 and vIL-6, show higher C-reactive protein (CRP), worse hyponatremia, higher KSHV viral load, and higher IL-10 compared to those who have higher expression levels of only hIL-6." (PMID 39772207, 2024). "In the multivariable analysis, hyponatremia (serum Na < 135 mmol/L) at presentation remained independently associated with adverse outcomes after adjusting for older age, vaccination status, lack of medical co-morbidities, year of admission, elevated CRP, LDH, and ferritin levels." (PMID 39204294, 2024). "Laboratory tests showed hyperferritinemia, hyponatremia, high erythrocyte sedimentation rate (ESR) and C-reactive protein (CRP), prolonged clotting times, and high titers of anti-SARS-CoV-2 IgG antibodies." (PMID 38543912, 2024). "The following six conditions were rewarded one point if present: fever > 39.4 °C; dry cough; hyponatremia (sodium) < 133 mmol/L; lactate dehydrogenase (LDH) > 225 mmol/L; C-reactive protein (CRP) > 187 mg/L and platelet count < 171 × 109/L." (PMID 35534798, 2022). "On the other hand, we determined hyponatremia, hypochloremia and elevated levels of AST, ALT, LDH and CRP in the COVID-positive patients, in comparison with the healthy controls." (PMID 35976368, 2022). "Control blood tests documented further increased inflammatory indices (CRP 166 mg/l, PCT 4.1 ng/ml), fibrinogen (640 mg/dl), ferritin (521 ng/ml), IL-6 (70.7 pg/ml), and a worsening hyponatremia (132 mmol/l)." (PMID 34422717, 2021). "The blood test showed persistence of hyponatremia (131 mmol/l), an increase in BNP (3,486 pg/ml), CRP (109.5 mg/l), and a reduction of troponin I (124.6 pg/mL)." (PMID 34422717, 2021). "Laboratory results revealed hyponatremia (sodium, 135 mmol/L), a serum white blood cell (WBC) count of 10.23 × 109/L (monocytes 11%), C-reactive protein (CRP) of 9.50 mg/L, serum EBV antibodies showed VCA IgG (+), EBNA-1 IgG (–), and EBV IgM (–)." (PMID 31764808, 2019). "In our study, the WBC and CRP levels in children with acute tonsillopharyngitis were higher than they were in the other groups, and we speculate that the degree of inflammation rather than the inflammatory site might be involved in the development of hyponatremia." (PMID 30405154, 2018). "The AUC value of age (0.586, P < 0.0001, 95% CI: 0.559–0.613), CRP (0.599, P < 0.0001, 95% CI: 0.571–0.628), and BUN (0.559, P < 0.0001, 95% CI: 0.531–0.588) were all significant predictors of hyponatremia." (PMID 30405154, 2018). "Patients with hyponatremia revealed significantly higher levels of inflammation, as indicated by white blood cells, NLR, RDW, and CRP, than those with normonatremia." (PMID 27622451, 2016). "Although no significant statistical correlation was found between hyponatremia and inflammatory markers like CRP, ESR, procalcitonin, or IL-6, hyponatremia was more common in severe cases and often approached critical levels." (PMID 39451561, 2024). "This patient's clinical features excluded hyponatremia, cough, and platelet abnormalities, while C-reactive protein and lactate dehydrogenase labs were not ordered." (PMID 37779758, 2023). "Blood examinations found hyponatremia (Na 131 mmol/L) and a slight increase in C-reactive protein serum levels (CRP 5 mg/dL), without an increase of white cells." (PMID 36900053, 2023). "In this study of a large cohort from a tertiary care hospital in a non-endemic area of TB, 0.07% [0.06; 0.09%] of patients presenting with hyponatremia and 0.28% [0.06%; 0.80%] with SIADH, but especially younger patients and patients with high CRP values, were diagnosed with TB." (PMID 36227934, 2022).
Hyponatremia (continued). "In this study of a large cohort from a tertiary care hospital in a non-endemic area of TB, 0.07% of patients presenting with hyponatremia, but especially younger patients and patients with high CRP values, were diagnosed with TB." (PMID 36227934, 2022). "Accordingly, there were significant differences between the two groups in Child-Pugh classification, peripheral blood WBC, serum CRP, serum TBiL, ascites WBC, ascites ALB, upper gastrointestinal hemorrhage, hepatorenal syndrome, hepatic encephalopathy and hyponatremia." (PMID 30788303, 2018). "CRP levels were higher in SLE patients with hyponatremia than those without with a borderline significance (p = 0.077)." (PMID 27193532, 2016). "Although, inflammation-related indicators, such as CRP and white blood cell count, and infection focus were not identified as independent risk factors for LZD-associated hyponatremia in this study, the severity of infection would play a role in developing hyponatremia." (PMID 40542403, 2025). "It was proposed that the degree of inflammation reflected as raised white blood count (WBC) and increased C-reactive protein (CRP), rather than the site of inflammation, might be involved in the development of hyponatremia." (PMID 36556138, 2022). "Blood tests at admission reported hyponatremia and hyperkalemia (Na+ 126 mmol/L, K+ 5.6 mmol/L, bicarbonate 22.3 mmol/L, creatinine 20 μmol/L, urea 5.4 mmol/L, white blood cells (WBC) 9.2 × 109/L, hemoglobin (Hb) 10.9 g/dL, platelets (Plt) 553 × 109/L, C-reactive protein (CRP) < 5 mg/L)." (PMID 34099019, 2021). "In children with hyponatremia, the age at admission was significantly older (P < 0.0001), male gender was more frequent (P = 0.019), CRP was higher (P < 0.0001), and coinfection with multiple organisms was more common (P = 0.001) than in children without hyponatremia." (PMID 30405154, 2018).
periodontal disease (205 papers, 2009 to 2026). "Nonetheless, the results showed that the severity of the periodontal disease was associated with greater CRP levels." (PMID 40362598, 2025). "One study in patients with kidney disease indicates that the periodontal disease is associated with higher level of high-sensitivity CRP." (PMID 40761740, 2025). "C-reactive protein (CRP), for example, is a well-known inflammatory marker that has been associated not only with periodontal disease and cardiovascular risk but also with peri-implantitis." (PMID 39062501, 2024). "Advanced periodontal disease and elevated C-reactive protein (CRP) were both associated with low vitamin C. This discovery is likely biologically significant." (PMID 38920853, 2024). "In in vivo studies, systemic low-grade inflammation after experimental periodontal disease was associated with increased gene expression for adipose tissue levels of interleukin (IL)-6 and C-reactive protein (CRP) in a rat model." (PMID 36767065, 2023). "Periodontal disease can cause low-grade systemic inflammation, which can elevate the level of inflammatory mediators such as IL-1, IL-6 and C-reactive protein." (PMID 36985292, 2023). "Periodontal disease status was evaluated; serum levels of leptin, adiponectin, and CRP were determined by enzyme-linked immunosorbent assay at baseline, as well as at 3 and 6 months after NSPT." (PMID 33603787, 2021). "We validated many of the studies’ original findings, but also identified new features associated with periodontal disease, including the genera Schwartzia and Aerococcus and the cytokine C-reactive protein (CRP)." (PMID 34079525, 2021). "Periodontal diseases can cause inflammation and immune responses, both locally and systematically (increasing white blood cell count, CRP, fibrinogens, cell adhesion molecules, and pro-inflammatory cytokines)." (PMID 35052354, 2021). "It constitutes, namely, the first report of its kind in Latin American women, contributing to the scant worldwide evidence about the serum and local CRP levels associated with cardiovascular risk in periodontal diseases." (PMID 34439905, 2021). "CRP is recognised to be elevated in some patients with periodontal disease, and in those people, treatment is associated with lowering of CRP." (PMID 32731485, 2020). "Many mediators of inflammation in periodontal disease are associated with cancer risk, such as C-reactive protein (CRP), Matrix metalloprotenases (MMP), Tumor Necrosis Factor (TNF), and Interluekin (IL)." (PMID 30754693, 2019). "There is the possibility that hs-CRP levels are a better indicator of the inflammatory status caused by periodontal disease in HD patients." (PMID 31382656, 2019). "In our present analysis, pooled data from two studies which adjusted CRP levels confirmed the association between periodontal disease and all-cause death in CKD individuals as well." (PMID 28814274, 2017). "Plenty of evidence manifested that periodontal disease is linked with an increase of several markers of chronic inflammation, such as C-reactive protein (CRP), interleukin-6 and fibrinogen." (PMID 28814274, 2017). "In pregnancy, the finding that caries was associated with higher CRP is consistent with reports showing that periodontal disease is associated with elevated CRP in pregnancy and correlated with CRP." (PMID 28571565, 2017). "Increased serum CRP also occurs in lower grade inflammatory processes, associating positively with the severity of periodontal diseases." (PMID 28578371, 2017). "In a population in India, periodontal disease was associated with increased levels of C-reactive protein (CRP) and also with pre-term birth." (PMID 26106385, 2015). "Elevated levels of cell-mediated and cytokine-mediated markers of inflammation-including CRP and other cytokines-are reported to be associated with periodontal disease." (PMID 26644840, 2015).